MAOA (monoamine oxidase A)
Diseases named in the same sentence as MAOA in open-access papers (continued):
Sharing a sentence is not in itself a finding about the gene and the disease.
tumor (continued). "Contrary to the carcinogenesis effect of MAOA positively related CEGs, the MAOA negatively related CEGs exhibit an anti‐tumor biological function by promoting T cell activation while participating in coding the MHC class II protein complex." (PMID 32931665, 2020). "Conversely, the inhibition of MAOA by the inhibitor clorgyline attenuated the proliferation of PCa cells and inhibited tumor growth and metastasis in mouse xenograft models." (PMID 30974737, 2019). "In general, MAOA functions as a tumor suppressor by reducing biogenic amines that stimulate tumor progression through increasing their degradation." (PMID 28402333, 2017). "An important area of inquiry centers on defining the mechanism(s) by which monoamine oxidases modulate tumor growth and chemotherapy resistance, and the corollary studies to determine how inhibitors of MAOA enhance chemotherapy sensitivity." (PMID 25198178, 2014). "MAOA expression markedly influenced tumor growth with grafts of PC3 cells overexpressing MAOA averaging tumor volumes 5-fold greater than grafts comprised of control PC3 cells (p<0.01)." (PMID 25198178, 2014). "The majority of patients (90%) had at least one tumor with high MAOA expression (staining score ≥1), and concordant MAOA expression across multiple tumors (range 2–7 tumors per patient) from the same individual was evident." (PMID 25198178, 2014). "Therefore, it is advantageous to have serum albumin first binding as a carrier to enhance drug-delivery then ultimately reach its target, the MAOA-expressing tumor." (PMID 39904854, 2025). "Where all genes, except for MAOA,CLU, and SIK2, were associated with poor tumour prognosis." (PMID 40028162, 2025). "We previously showed NMI biodistribution in many tissues of WT mice that correspond to MAOA expression, and indeed tissues with high MAOA such as lung, liver, kidney, and tumor had very high NMI signal whereas low MAOA expression tissues such as adipose and spleen had low signal." (PMID 39904854, 2025). "MAOA also helped regulate the T cell functions of TAMs in three-dimensional-culture experiments designed to ensure that key immune features of the natural TME were preserved, suggesting that MAOA-targeted TAM immunotherapy can modulate tumor immune responses from multiple angles." (PMID 38349393, 2024). "Moreover, the expression of MAOA was significantly correlated with the lymph node metastasis status, tumor stage, gender, and smoking status." (PMID 33763378, 2021). "In conclusion, our findings indicate that MAOA functions as a tumor suppressor in LUAD." (PMID 33763378, 2021). "Subsequently, we analyzed 32 paired tumor-normal tissue samples for NE synthase and degrading enzyme mRNA expression in TCGA database, and the MAOA (p ≤ 0.001) and MAOB (p ≤ 0.001) mRNA levels showed significantly higher expression in normal tissues than in the paired tumor tissues." (PMID 33855088, 2021). "Our results reveal the tumor suppressive role of MAOA in LUAD growth." (PMID 33763378, 2021). "Given that NE is closely related to the regulation of numerous immune cells in the tumor immune microenvironment, we conducted an analysis of relevant indicators for the clinical evaluation of immunotherapy results with its degrading enzyme MAOA." (PMID 33855088, 2021). "There is a variety of reports on tumor suppression and the promotion of MAOA." (PMID 34209963, 2021). "In 18 of the 31 cases (58%) MAOA expression increased following treatment, and corresponding increases in MAOA protein levels were observed in three of three cases with elevated MAOA transcripts and sufficient tumor material in both pre- and post-treatment samples." (PMID 25198178, 2014). "Importantly, MAOA was also identified in the NMI-labeled band for MC-38 tumor samples." (PMID 39904854, 2025).
tumor (continued). "MAOA expression has been observed in DCs, similar to macrophages, and targeting MAOA in DCs for immunomodulation or metabolic regulation may provide new directions and possibilities for future tumor immunotherapy." (PMID 38349393, 2024). "Moreover, high MAOA expression was found to be significantly associated with higher tumor stage, GS, and PSA, Which was consistent with the previous study implying MAOA expression was significantly elevated in Gleason 4 or 5 samples relative to Gleason 3 samples." (PMID 37403079, 2023). "Interestingly, we found that NC could exert its partial anti‐tumor effect by influencing the expression of MAOA. a decreased MAOA was detected in HCC patients and correlated with poor prognosis." (PMID 32931665, 2020). "However, both tumor suppression and promotion characteristics of MAOA have been identified." (PMID 28402333, 2017). "After adjusting for Gleason grade, the expression change of MAOA was marginally associated with time to PSA relapse (hazard ratio = 1.55, p = 0.068): the reduction in hazard ratio suggests that MAOA expression and status of tumor differentiation are associated." (PMID 25198178, 2014). "Monoamine oxidases (MAOA and MAOB) are mitochondrial enzymes that degrade various monoamine neurotransmitters, which have been recognized as important regulators of tumor progression." (PMID 41338163, 2025). "The results revealed that the expression of MAOA, AKR1A1, ALDH9A1, HAAO, and ALDH2 was significantly downregulated in ESCC tumor tissues compared to non-tumor tissues." (PMID 40821701, 2025). "Ultimately, our investigation into JARID1D-mediated signaling within the tumor-bone cell interaction revealed that following JIB-04 treatment, there was upregulation of JARID1D, whereas MAOA and JunD expression were downregulated." (PMID 39816691, 2025). "A subset of solid tumors (e.g., prostate cancer, PCa) co-express/co-localize MAOA within the TME, which comprises various cell types such as tumor cells, immune cells, and mesenchymal cells." (PMID 38349393, 2024). "We also identified the MAOB and MAOA genes to be under selection, where MAOB has been shown to be correlated with HiF-1α (tumour grade and hypoxia-inducible transcription factor)." (PMID 38500079, 2024). "MAOA acted as an autoregulatory factor that directly affected the direction of TAM polarization, thereby affecting the antitumor activity of T cells and tumor growth." (PMID 38349393, 2024). "Therefore, MAOA-mediated modulation of ROS/IL-6 interactions may create a harmful cycle that promotes the transformation of naïve stroma into a phenotype that supports tumor growth." (PMID 39092186, 2024). "The MAOA gene was readily induced in tumor-infiltrating CD8+ T cells, and MAOA expression levels positively correlated with T cell exhaustion and a dysfunctional status." (PMID 38349393, 2024). "Monoamine oxidase A (MAO-A) inhibition treatment induces TAM reprogramming and suppresses tumor growth in preclinical mouse syngeneic and human xenograft tumor models." (PMID 36739406, 2023). "The H-scores of MAOA (T; p = 0.005) and MAOB (T; p = 0.006) in tumor cells (T) were high in ACN, whereas LOX (T, S; p < 0.001) in tumor and stromal cells (S) and AOC3 (T; p < 0.001) were higher in PCC." (PMID 37509535, 2023). "Monoamine Oxidase-A (MAO-A) enzyme mediates the production of reactive oxygen species (ROS) that trigger DNA damage and oxidative injury of cells resulting in tumor initiation and progression." (PMID 35566238, 2022). "The genes up-regulated in the tumor tissues included ATP citrate lyase (ACLY) and monoamine oxidase A (MAOA)." (PMID 36090054, 2022). "This in silico analysis in large tumor datasets demonstrated that the expression levels of TH, DDC, and DBH were reduced in NB compared to PHEO/PGL, inversely to MAOA levels." (PMID 36531507, 2022). "We found that Patient CASE 1, with a high SUVmax value and glycolysis, showed low MAOA and MAOB expression in the tumor tissue." (PMID 33855088, 2021).
tumor (continued). "Patient CASE 2, who had a low SUVmax value and glycolysis, showed high MAOA and MAOB expression in the tumor tissue." (PMID 33855088, 2021). "The MAOA (p ≤ 0.001) and MAOB (p ≤ 0.001) mRNA levels were significantly higher in normal tissues than in tumor tissues." (PMID 33855088, 2021). "They found that MAOA hampers HCC metastasis by inhibiting the epinephrine system, which mediates the metastasis of tumor cells by binding to a specific receptor and transactivating the EGFR signal pathway." (PMID 32931665, 2020). "Herein, a series of novel conjugates combining the MAOA inhibitor isoniazid (INH) and tumor-targeting near-infrared (NIR) heptamethine cyanine dyes were designed and synthesized." (PMID 30974737, 2019). "Furthermore, JIB-04 diminished the expression levels of key metastatic mediators, including MAOA, JunD, and RANKL, within metastatic tumor tissues while activating JARID1D." (PMID 39816691, 2025). "Monoamine oxidase A (MAOA), primarily known as a mitochondrial enzyme in the brain and as an immune checkpoint in antitumor therapy, also negatively regulates the Trp metabolism-mediated anti-ferroptotic pathways that promote tumor growth." (PMID 40821701, 2025). "While the contrasting roles of MAOA and MAOB in PCa progression remain unexplained, we speculated that distinct substrates may modulate the tumour‐suppressive activities of MAOB and oncoprotein activities of MAOA." (PMID 38520217, 2024). "Collectively, while MAOA was reported to be an oncogene, our findings from gene correlation and expression analyses suggest that MAOB may potentially function as a tumour‐suppressive gene in PCa." (PMID 38520217, 2024). "This negative feedback loop reveals MAOA as a new immune checkpoint that functions as a negative feedback regulator induced by tumor antigen recognition that suppresses the antitumor responsiveness of CD8+ T cells." (PMID 38349393, 2024). "Clorgyline, a MAOA inhibitor, effectively suppresses tumor development in mice, increasing caspase three levels and decreasing IL-6, pSTAT3, STAT3, and CD44 production in tumor cells." (PMID 39092186, 2024). "MAOA (T; p = 0.005) and MAOB (T; p = 0.006) in tumor cells were higher in ACN, whereas LOX was higher in tumor cells (T; p < 0.001) and LOX in stromal cells (S; p < 0.001) and AOC3 in tumor cells (T; p < 0.001) were higher in PCC." (PMID 37509535, 2023). "Because MAOA and MAOB functioned in dopamine degradation, we hypothesized that elevated HIF-1A might decrease the dopamine in MES-like high tumor." (PMID 36720864, 2023). "However, within the amine oxidase family, MAOA and MAOB staining demonstrated evidence of intratumoral heterogeneity, with expression observed in only certain parts of the tumor area in minor cases." (PMID 37509535, 2023). "MAPKAPK2, MAOA, and EPHX2 were demonstrated to affect tumour development in various contexts." (PMID 36826154, 2023). "Elevated norepinephrine is related to activated glycolysis, so the levels of MAOA and MAOB in tumor tissues are closely related to the prognosis of patients with PD-1 and other immunotherapy.However, these conclusions were based on the finding that tumor cells consume high levels of glucose." (PMID 36387147, 2022). "MAOA promoted PCa metastasis by regulating downstream ROS and Twist1 pathways that mediated Shh/Gli signaling to activate YAP1 transcription in concert with AR to induce epithelial–mesenchymal transition and tumor–stromal cell interactions." (PMID 36452480, 2022). "In light of the present study, it is reasonable to suppose that NC may attenuate tumor cell growth and other malignant behaviors in HCC by increasing the MAOA expression." (PMID 32931665, 2020). "We found that the levels of MAOA mRNA were significantly decreased in five cell lines (NP460hTert, CNE1, CNE2, HONE1 and SUNE1) infected with EBV with the exception of HK1 which was derived from a well-differentiated NPC tumour (p < 0.001)." (PMID 32273550, 2020).
tumor (continued). "Tumors expressing low levels of MAOA may generate less oncostatic 5-HIAA and at the same time contain higher levels of 5-HT, which can promote tumor growth and survival via cross-talk to the RAS/MAPK pathway." (PMID 25978500, 2015). "For [18F]FDOPA studies, tumour-bearing mice and sham-operated controls were pretreated with enzyme inhibitors of aromatic amino acid decarboxylase (AADC), catechol-O-methyl transferase (COMT), monoamine oxidase A (MAO-A) or a combination of COMT and MAO-A." (PMID 23497589, 2013). "MAOA induces osteoclastogenesis by triggering the production and release of IL-6 and RANKL from osteoblasts, which is dependent on the transcription factors Gli1 and Gli2 expressed in osteoblasts while activated by Shh molecules secreted from tumor cells in the presence of MAOA." (PMID 36860320, 2023). "Of note, these whole-tumor lysate transcriptome data analyses could not localise the MAOA expression to a specific cell type (e.g., TAMs); future studies of quality transcriptome data generated from single cells or sorted TAMs are needed to obtain such information." (PMID 34112755, 2021). "The expression of MAOA, AKR1A1, ALDH9A1, HAAO, and ALDH2 was significantly downregulated in ESCC tumor tissues compared to non-tumor tissues." (PMID 40821701, 2025). "Meanwhile, MAOA and MAOB were detected to be downregulated, meaning that the additional tumor derived dopamine would not be degenerated in time." (PMID 33898321, 2021).
neurological disorders (23 papers, 2009 to 2025). "Alterations in MAOA expression are associated with behavioural and neurological disorders." (PMID 39319049, 2024). "Interestingly, the enriched pathways of WM15 involve pathways associated with neurological disorders, and monoamine oxidase A (MAOA), a mitochondrial enzyme, is related to these pathways." (PMID 32616892, 2020). "Monoamine oxidase A (MAO-A) is an enzyme best known for its function in the brain; small molecule MAO inhibitors (MAOIs) are clinically used for treating neurological disorders." (PMID 34112755, 2021).
neurodegenerative disease (13 papers, 2012 to 2025). A disorder of the central nervous system characterized by gradual and progressive loss of neural tissue and neurologic function. "With their acute neurotransmitter- and cathecolamine-oxidizingactivities, MAOA and MAOB are among the principal enzymatic sourcesof ROS and are implicated in various neurodegenerative diseases." (PMID 40042998, 2025). "Recent studies have also shown that Monoamine oxidase A (MAO-A) has the potential to play a role in the disease-modifying treatment of neurodegenerative diseases." (PMID 35799585, 2022). "Inhibitors of monoamine oxidase A (MAO-A) and monoamine oxidase B (MAO-B) are clinically used to treat psychiatric and neurodegenerative diseases, respectively." (PMID 40076286, 2025).
infection (7 papers, 2016 to 2023). The state of being infected such as from the introduction of a foreign agent such as serum, vaccine, antigenic substance or organism. "The expression of mRNAs for Cadherin, Albumin, GstA4 and AFP were significantly increased 20 and 40 days after the first infection and those for MaoA and MaoB were augmented to some extent." (PMID 28352551, 2016). "MAOA also significantly reduced cell proliferation at 72 h after the infection of the lentivirus." (PMID 33763378, 2021). "Our results showed that the expression of MAOA protein was significantly stronger in HPV-16 E7-overexpressing cells than that in empty vector and mock infection controls." (PMID 32792865, 2020). "Higher mRNA levels of MAOA, MAOB and VMAT2 were observed upon infection in these cells also, while DBH and COMT expression was not significantly altered." (PMID 36611805, 2022).
prostate (3 papers, 2017 to 2025). "Monoamine oxidase A (MAOA) is a mitochondrial enzyme; its upregulation in stromal compartments has been linked to prostate tumorigenesis." (PMID 41514658, 2025).
metabolic disease (2 papers, 2020 to 2022). A congenital disorder (due to inherited enzyme abnormality) or acquired (due to failure of a metabolically important organ) disorder resulting from an abnormal metabolic process. "The finding that inhibition of MAOA can induce human adipocyte beiging in vivo suggests brain impenetrable, adipocyte favoring formulations of MAOA inhibitors as potential therapeutic agents in metabolic disease." (PMID 36107478, 2022). "Our results reveal species-specific cell type dependencies controlling the development of thermogenic adipose tissue and point to human adipocyte MAOA as a potential target for metabolic disease therapy." (PMID 36107478, 2022).
inflammation (1 paper, 2021). Aberrant reaction of the microcirculation characterized by movement of fluid and leukocytes from the blood into extravascular tissues. "Our results showed that systolic cardiac dysfunction in Tg MAOA mice was strongly correlated with oxidative stress induced premature senescence of cardiac stromal cells favoring the recruitment of CCR2+ monocytes and the installation of cardiac inflammation." (PMID 33668142, 2021).
MAOA also shares sentences with these, for which no sentence is quoted: Parkinson’s (10 papers); cardiac diseases (5); dementia (5); endothelial dysfunction (5); type 2 diabetes (5); post-traumatic stress disorder (4); prostate adenocarcinoma (4); adenocarcinoma (3); cardiovascular diseases (3); ischemia (3); nasopharyngeal carcinoma (3); non-small cell lung carcinoma (3); Norrie disease (3); Oppositional defiant disorder (3); pheochromocytoma (3); vivax malaria (3); Arrhythmia (2); asthma (2); autism spectrum disorder (2); cognitive disorder (2); gastric tumor (2); genetic disease (2); gestational diabetes mellitus (2); glaucoma (2); Huntington disease (2); kidney cancer (2); left ventricular hypertrophy (2); liver cancer (2); myocardial infarction (2); neurodevelopmental disorder (2).
A further 87 diseases each share a sentence with MAOA in 2 papers or fewer.